NRAS (NRAS proto-oncogene, GTPase)
Diseases named in the same sentence as NRAS in open-access papers (continued):
Sharing a sentence is not in itself a finding about the gene and the disease.
tumor (continued). "The biomarker analyses of this study aimed to describe the biological impact of MEK-targeted inhibition of the MAPK pathway with binimetinib, establish the BRAF- and NRAS-mutated tumor genetic landscape, and explore the link between genetic pathway alterations and the response to binimetinib." (PMID 30956763, 2019). "The genotyping may be important to therapy strategies including use of mitogen-activated protein kinase kinase (MEK) inhibitors in NRAS-mutated tumours." (PMID 30782194, 2019). "Whether the NRAS mutation derives from a new lesion or is as a matter of fact a result of possible tumor heterogeneity can be hardly assessed confidently from blood as one cannot determine the location where the mutated fraction in the cfDNA came from." (PMID 31620244, 2019). "The vast majority (94.3%) of NRAS mutant tumours had an NRAS codon 61 mutation." (PMID 29755118, 2018). "Furthermore, around 50% of cases showed KRAS and/or NRAS mutations for each category of tumor cell content (27/54 in cases with <10% tumor cell content; 278/553 in those with 10–50% tumor cells; or 59/117 in cases with >50% tumor cells)." (PMID 29755687, 2018). "The results of this study contribute to a greater understanding of disease biology among tumours harbouring these somatic mutations and suggest that BRAF/NRAS mutant tumours may be more potent drivers of aggressive tumour biology." (PMID 29755118, 2018). "We created such a model using hydrodynamic injection and a transposon system to introduce AKT and NRAS and open reading frames (ORFs) encoding surrogate tumor antigens and luciferase into chromosomes of hepatocytes to induce nodular and diffuse tumors in the liver." (PMID 30526672, 2018). "In addition to known activating NRAS mutations in 18% (11/63) of tumours, we identified an activating KRAS G12A mutation." (PMID 29559732, 2018). "NRAS mutations were identified in 12 (3.4%) out of 353 tumor samples." (PMID 29666387, 2018). "We next tested whether NRAS mutation and overexpression are functionally involved in pulmonary metastasis and at which step: primary tumor escape or lung homing?" (PMID 28341702, 2017). "Indeed, labeled primary tumor cells disseminated into the blood independent from NRAS mutation status, but the latter was pivotal for pulmonary involvement by both s.c. and i.v. injected tumor cells." (PMID 28341702, 2017). "In total, 111 NRAS Q61 mutated tumors were collected with 60–95% tumor cells." (PMID 28668077, 2017). "Since BRAF and NRAS hotspot mutations are almost mutually exclusive there is close to a 97.6% probability that we would have found either a BRAF or an NRAS hotspot mutation in at least one of the tumours." (PMID 28806732, 2017). "We discovered that tumor cells of various tissues of origin that carry NRAS mutations are able to spontaneously metastasize to the lungs of mice from subcutaneous (s.c.)primary sites, while cancer cells with wild‐type NRAS cannot." (PMID 28341702, 2017). "Notably, Sample ID 1736 gained 4 somatic mutations and Sample ID 1461 gained 9 additional somatic mutations in the tumor samples (except for the inherited NRAS G138R and APC V1125A variant, respectively)." (PMID 27121310, 2016). "Only one tumor harboring complex BRAF/NRAS mutations showed weak tumor regression (−24%)." (PMID 26989027, 2016). "Patient 8 had NRAS mutation Q61K in approximately 94% of tumor cells and BRAF V600E in 4%." (PMID 25794135, 2015). "Different tumor types in which NRAS mutations have been described." (PMID 25277205, 2014).
tumor (continued). "All NRAS mutations found in the tumor samples were heterozygous somatic mutations." (PMID 25254041, 2014). "Similarly, a poorer survival of metastatic patients with BRAF or NRAS tumor mutations and of patients with BRAF-mutant tumors after treatment with temozolomide and bevacizumab was reported before." (PMID 24586605, 2014). "Similarly, a worse prognosis of metastatic patients with BRAF or NRAS tumor mutations and of patients with BRAF mutant tumors after treatment with temozolomide and bevacizumab was reported before." (PMID 24475086, 2014). "Comparison of the clinicopathological features of the mutated KRAS, PIK3CA, NRAS genes with an all-wild type of these genes showed that the frequency of the intestinal type was significantly higher in patients whose tumor tissue contained KRAS mutations (P = 0.014)." (PMID 24774510, 2014). "While the data currently presented should be interpreted carefully due to the limited number of patients studied, the association of low BRAF and NRAS expression with benefit from anti-tumor therapy as well as improved relapse-free and overall survival is interesting." (PMID 23673558, 2013). "Furthermore, NRAS mutation occurred more frequently in distant metastasis tumors (12.2% vs 3.3%, P = 0.010), and different tumor stage showed a different NRAS mutation rate (P = 0.030)." (PMID 24339949, 2013). "The NRAS G12D mutation was found in both FFPE tumor and plasma from a patient with ACUP." (PMID 23144797, 2012). "Tumors with MET and NRAS mutations also have an unexpectedly high frequency of co-occurring mutations, which suggests that they occur as a second mutation and perhaps later in the etiology of the tumor." (PMID 20233444, 2010). "Also, the rs14804 of the NRAS gene shows a protective effect for the CC genotype, while the presence of the T allele is associated with advanced disease stages and lymph node involvement, suggesting its possible role in tumor invasion and metastasis." (PMID 39867023, 2024). "NRAS mutations may already exist as subclones within the tumor before treatment." (PMID 38067230, 2023). "While in normal cells, this would lead to cell cycle arrest, activating mutations in BRAF and NRAS, combined with mutation in tumor suppressors such as PTEN and can result in robust mitogenic signaling and translation of CCND1, which may “override” CDKN1A/p21-mediated checkpoint activation." (PMID 36696495, 2023). "Moreover, receiver operating characteristic (ROC) curves for maximum standard uptake value (SUVmax) of the primary tumor were generated along with analysis of the target tissue to nontarget tissue ratio (T/NT) for predicting the efficacy of KRAS/NRAS/BRAF mutations in CRC." (PMID 34239564, 2021). "A lower ctDNA detectability could be a characteristic of NRAS-mutated tumours." (PMID 32664549, 2020). "Finally, EGFR and NRAS mutations are rare in all these three tumor entities." (PMID 27283768, 2016). "Thus, targeting inhibition of MAPK-ERK signal pathways in cells that harboring KRAS, NRAS or BRAF mutation could suppress tumor growth." (PMID 26567773, 2015). "KRAS, NRAS, BRAF, and PIK3CA mutations occur at different frequencies in CRC and exert distinct effects on tumor biology, including the composition and functional properties of the TME, particularly its immune component." (PMID 41596586, 2026). "NRAS mutations typically arise at a later stage of tumor progression and are often observed either alone or in combination with a KRAS mutation during tumor recurrence." (PMID 41488286, 2026).
tumor (continued). "This study aimed to evaluate the association between primary tumor sidedness, KRAS/NRAS/BRAF mutational status, and VTE occurrence in patients with mCRC treated in the outpatient setting." (PMID 41751211, 2026). "Multivariate logistic regression determined the association between (i) NRAS and KIT testing and patient/tumour characteristics, and (ii) NRAS genotype and patient/tumour characteristics." (PMID 41378737, 2026). "NRAS codon 61 mutations were the most common alterations, followed by BRAF V600E, consistent with known molecular patterns in follicular-derived neoplasms." (PMID 41595518, 2026). "Molecular profiling identified NRAS Q61R and TERT promoter mutations, equivocal MYC amplification, and an elevated tumor mutational burden." (PMID 42158418, 2026). "This study highlights the prognostic significance of HIF-1α, LOX and ITGA5 expression in the tumor microenvironment, particularly in the context of KRAS/NRAS/BRAF mutation status." (PMID 39857068, 2025). "Other predictive markers include mutations in KRAS/NRAS and BRAF V600E, tumor mutational burden, and imaging-based radiomic parameters such as metabolic tumor volume (MTV) and total lesion glycolysis on PET/CT." (PMID 41002551, 2025). "NRAS mutations can lead to continuous activation of the MAPK pathway, which promotes cell proliferation and tumor growth." (PMID 40526090, 2025). "Inspection of variants in genes linked to anti‐EGFR therapy (KRAS, BRAF, NRAS, PTEN and PIK3CA) revealed variability across tumours and fractions." (PMID 40302146, 2025). "For example, driver mutations of RAS genes (KRAS type, NRAS, and HRAS) lead to infinite proliferation and enhanced survival of tumor cells." (PMID 40778223, 2025). "If the average F1 score improved by more than 5%—as observed for genes like BRAF, ATRX, and NRAS— selected tumour types were utilized for downstream analysis." (PMID 40775769, 2025). "Our observations indicated a significant reduction of the average tumor size within the NRAS ASO-1 treatment group compared to the Control ASO group." (PMID 40473796, 2025). "Co-delivery of oncogenic AKT and NRAS with either a control vector or GCDH expression plasmid into the livers of C57BL/6 mice led to full tumor penetrance in both groups." (PMID 40896397, 2025). "Clinically, molecular biomarkers—including KRAS/NRAS/BRAF mutations, HER2 amplification, PIK3CA mutations, MSI/MMR status, and the tumor microenvironment—play an important role in therapeutic decision-making." (PMID 40805234, 2025). "The mutational profile of CRC tumors, including KRAS, NRAS, BRAF, PIK3CA, and AKT1 gene mutation and MSI status significantly influences the characteristics of the tumor microenvironment (TME) and directly impacts patient prognosis." (PMID 40724985, 2025). "The differences are unreliable; however, there is a tendency towards a rarer detection of high-risk aberrations in patients with the KRAS, NRAS, and BRAF gene mutations at any tumor locus." (PMID 40943426, 2025).
tumor (continued). "Further evaluation of the tumor by Caris Molecular Intelligence revealed several mutations, including the NF1 variant of uncertain significance (VUS), NRAS, PBRM1, FAT1, TERT Promoter, and ATM." (PMID 40125165, 2025). "The RAS family of small GTPases (including HRAS, KRAS, and NRAS) plays pivotal roles in tumor progression." (PMID 40919428, 2025). "In patients with KRAS, NRAS or BRAF mutation and the moderate to strong expression of all three of these proteins in the tumor microenvironment, the number of metastatic lymph nodes was higher than in other patients." (PMID 39857068, 2025). "Class I mutations exclusively co-occurred with BRAF or NRAS mutations, while Class II and III mutations often acted as sole tumour drivers." (PMID 40107205, 2025). "While anti-EGFR treatments target the EGFR pathway to inhibit tumor growth, NRAS mutations can activate downstream signaling pathways independently of EGFR, allowing tumor cells to evade EGFR blockade and continue proliferating." (PMID 40526090, 2025). "Mutations in NRAS and KIT similarly enhance MAPK signaling, contributing to tumor growth and metastasis." (PMID 40507265, 2025). "Patterns of CNAs vary with genetic backgrounds, with BRAF/NRAS wild-type tumours showing notable increases." (PMID 40831998, 2025). "These include BRAF, NRAS, and NF1 mutations, which provide insight into tumor biology and guide therapeutic decisions." (PMID 40507265, 2025). "These insights offer a compelling framework for overcoming therapeutic resistance and reprogramming the tumor immune microenvironment to activate the cytotoxic T-cells and enhance the responses to immunotherapy in NRAS-driven cancers." (PMID 40563669, 2025). "Quantitative analysis of tumor-specific mutations in ctDNA, such as single nucleotide variants in KRAS, NRAS, PIK3CA, BRAF, and EGFR, demonstrated over 80 % concordance with tumor tissue in patients with colorectal, lung, and breast cancers." (PMID 40144458, 2025). "Then, we measured the expression levels of MITF, BRAF and NRAS in the annotated cell types, which revealed increased expression of the two former genes in the tumour cells, compared to the microenvironment." (PMID 41168392, 2025). "In this same context, a prospective study, including 43 MM patients, BRAF, NRAS and KIT mutations in ctDNA and basal concentration were analyzed using ddPCR and correlated with basal and changes in tumor burden and OS (p < 0.05)." (PMID 39859576, 2025). "The clinical information of the patients from whom the samples were derived varied, including factors such as age, sex, tumor (benign or malignant) infiltration depth, and BRAF and NRAS mutation status." (PMID 40098976, 2025). "Molecular analysis identified a KRAS/NRAS wild-type tumor, which allowed the use of panitumumab as a targeted therapy." (PMID 40863225, 2025). "We also used Sanger sequencing to detect six genes—KRAS, NRAS, HRAS, TERT, RET, and BRAF—in the tumor tissue and identified a C228T mutation in the TERT promoter region." (PMID 41488090, 2025). "Mutations in neurofibromatosis-related protein (NF1), NRAS, and HRAS genes were found in tumours that developed resistance to lorlatinib or ceritinib, and NF1 loss conferred resistance to ALK inhibitors in NB cells." (PMID 41511287, 2025). "In the following years, retrospective analysis of RAS (KRAS, NRAS) and BRAF mutations in tumor tissue samples from patients included in these pivotal trials showed a greater benefit in patients with tumors not harboring RAS/BRAF mutations." (PMID 38711991, 2024).
tumor (continued). "Circulating tumor DNA (ctDNA) can reveal mutations in genes such as KRAS, NRAS, and BRAF and help tailor personalized treatment strategies." (PMID 38790167, 2024). "As for NRAS, moderate-impact alterations in this gene prevailed in lgOvCa in comparison with the three remaining tumor groups." (PMID 39456660, 2024). "Tumor mutation status was analyzed, resulting into BRAF wildtype and NRAS mutated in Q61X, while expression of PD-1 ligand was < 1%." (PMID 39148899, 2024). "The coexistence of BRAF and NRAS mutations was noted in eight tumor specimens, while seven samples tested as wild-type (WT) for both BRAF and NRAS genes." (PMID 38396984, 2024). "Several tumor factors are believed to be crucial, such as the existence of oncogenic BRAF or NRAS mutations." (PMID 38339344, 2024). "Out of 86 tumor samples, 40 (46.5%) harbored somatic mutations within actionable genes (BRAF: 2.3%, KRAS: 43%, NRAS: 2.3%)." (PMID 39635441, 2024). "NRAS mutations at codons 12 and 61 activate pathways including IL1, JAK/STAT, and NF-κB, promoting an inflammatory tumor microenvironment, enhancing cell proliferation and survival, and contributing to therapy resistance." (PMID 39684219, 2024). "Overexpression of ARQ62L or ARE81Q promoted NRAS-dependent tumor development, as evidenced by the size of gross tumor nodules and liver weight." (PMID 38182647, 2024). "Mutation of KRAS, neuroblastoma RAS viral (v-ras) oncogene homolog (NRAS), and Harvey rat sarcoma viral oncogene homolog (HRAS) are located in codon 12, with a frequency of 20 to 100% in tumor progression." (PMID 39057671, 2024). "Mutations in the genes encoding the components of the MAPK pathway, such as KRAS, NRAS, and BRAF, are frequently observed in LGSOCs, driving uncontrolled cell proliferation and tumor development." (PMID 39409889, 2024). "Age, gender, tumor tissue site, pathologic stage, Breslow thickness, ulceration, BRAF and NRAS mutation status were taken into consideration." (PMID 38438381, 2024). "The laboratory analysis revealed that, of the 33 samples from the tumor biopsies, 9 (27.3%) had mutations in the KRAS gene and 5 (15.1%) in the NRAS gene, in the genetic positions studied." (PMID 39816392, 2024). "Altogether, 83 FFPE tumor tissues from CRC patients listed in the NCI database were analyzed for microsatellite instability status, presence of BRAF and KRAS/NRAS mutations, and neoplastic cell percentage in tissue samples." (PMID 38539463, 2024). "Our study analyzed 83 CRC patient tumor tissues from the National Cancer Institute (NCI) database, examining microsatellite instability (MSI), BRAF, KRAS/NRAS mutations, and neoplastic cell percentage." (PMID 38539463, 2024). "Here, we showed that the lack of LIN28A and LIN28B had no impact on liver development or function, but largely abrogated tumor initiation driven by powerful oncogenes such as NRAS, CTNNB1, YAP, and AKT." (PMID 38875287, 2024). "Targeted therapies, including inhibitors targeting BRAF, MEK, c-KIT, and NRAS, are designed to block the specific molecules responsible for tumor growth." (PMID 38399429, 2024). "Based on 2022 guidelines from the American Society of Clinical Oncology, the decision to initiate anti-EGFR treatment should be guided by the primary tumor location and testing for BRAF and RAS (KRAS and NRAS) mutations and deficient mismatch repair or MSI2." (PMID 38347302, 2024). "As part of the trial, the mutation status of KRAS (exon 2, 3, and 4), NRAS (exon 2 and 3), and BRAF (codon 600) was previously assessed in tumor tissue." (PMID 39433569, 2024).